TNF (tumor necrosis factor)
Diseases named in the same sentence as TNF in open-access papers (continued):
Sharing a sentence is not in itself a finding about the gene and the disease.
cancer (continued). "Gene ontology (GO) analysis revealed that MPZ+ mSCs were significantly enriched in neuron apoptosis processes, neuron death, and tumor necrosis factor-mediated signaling pathways, possibly reflecting the damage response induced by cancer cell invasion." (PMID 40148311, 2025). "Recent research has also revealed that CA and plant extracts rich in CA alleviate the suppression of the NF-κB signaling pathway, consequently downregulating the expression of pro-inflammatory TNF-α in diverse inflammatory conditions and in cancer cell lines." (PMID 39910608, 2025). "M1 cells also produce ROS/RNS, leading to direct cancer cytotoxicity, as well as proinflammatory cytokines, including IL-12, IL-23, and TNFα, to recruit neighboring immune cells." (PMID 40724900, 2025). "TNF-α is a pro-inflammatory cytokine that plays a key role in the connection between chronic inflammation and cancer." (PMID 39941912, 2025). "To evaluate the contribution of TNFα to the inhibitory effects of cancer patient serum on muscle differentiation, we tested the effect of TNFα-neutralizing antibodies." (PMID 40283883, 2025). "Among the 18 patients who developed cancer, the mean duration of TNF inhibitor exposure before cancer diagnosis was 103.8 ± 50.7 months." (PMID 41302997, 2025). "The TNF pathway is crucial in initiating and progressing inflammatory and autoimmune disorders, cancer, and cardiovascular conditions." (PMID 40620796, 2025). "Studies have suggested that chronic inflammation, along with myeloid cell‐mediated ROS and tumor necrosis factor α (TNF‐α) signaling, can lead to invasive cancer." (PMID 40377005, 2025). "Previous studies have demonstrated robust cancer-induced systemic changes, characterized by elevated inflammatory mediators such as IL-6, TNF-α, CXCL10, and MMP9." (PMID 41153795, 2025). "These carcinogens induce chronic inflammation, promoting cancer progression through the release of pro-inflammatory cytokines (e.g., TNF, IL-6, IL-8, IL-1β), activation of transcription factors (e.g., NF-κB), and enhancement of angiogenesis." (PMID 40733296, 2025). "Despite its early promise as an anti-cancer agent, systemic administration of TNF-α in clinical trials led to unacceptable toxicity while showing limited efficacy." (PMID 40868199, 2025). "A significant increase in plasma TNF-α levels was observed in cancer patients following treatment with chemotherapy protocols that included DOX." (PMID 40358798, 2025). "The relationship between diet and cancer has drawn particular attention, as certain food additives may influence cellular processes linked to carcinogenesis for instance, by enhancing pro-inflammatory signaling pathways like nuclear factor kappa B (NF-κB) and tumor necrosis factor-alpha (TNF-α)." (PMID 41228538, 2025). "MSGA drived macrophages differentiation to the M1 subtype, which secretes pro-inflammatory cytokines (e.g., iNOS, TNFα) to suppress cancer cell viability." (PMID 40786029, 2025). "Participants who developed cancer were slightly older (73.4 ± 5.4 vs. 71.6 ± 5.9 years), more often female (53.2% vs. 45.0%), and displayed higher median plasma TNF-α concentrations (4.6 [3.3–6.1] pg." (PMID 41473193, 2025). "Tumor‐associated fibroblasts (CAFs) contribute to this process by secreting fatty acids and lipid‐related factors, such as leptin and tumor necrosis factor‐α (TNF‐α), which indirectly enhance cancer cell survival and angiogenesis." (PMID 40391753, 2025). "TWEAK activates NF-κB in myocytes through pathways that are similar to TNFα and IL-1, which results in the transcription In cancer cachexia, TWEAK–Fn14 signaling contributes to skeletal muscle wasting through multiple molecular mechanisms." (PMID 40869331, 2025). "Concurrently, TNF-α facilitates the release of Cyt c from mitochondria of ER-positive cancer cells, triggering apoptosis." (PMID 40688079, 2025).
cancer (continued). "This aligns with the systemic inflammatory response observed in cancer, where chronic inflammation drives neutrophilia while simultaneously suppressing albumin synthesis via cytokine-mediated pathways (e.g., IL-6 and TNF-α)." (PMID 40709341, 2025). "TILT-123 (igrelimogene litadenorepvec) is an engineered OVs that selectively replicates in cancer cells and expresses dual transgenes IL-2 and TNF-α, designed to enhance tumor immune infiltration and cytotoxic T-cell responses." (PMID 41024300, 2025). "Previous studies have indicated that IL-6 and TNF-α were pro-inflammatory cytokines, which mediate in many inflammatory diseases and contribute to developing autoimmune disorders and cancer." (PMID 40109962, 2025). "Tumor necrosis factor-α (TNF-α) is considered a potential therapeutic strategy for cancers, as it exacerbates calcium influx through voltage-gated calcium channels (VGCCs), thereby inducing apoptosis." (PMID 41415204, 2025). "In cancer cells, both SA and Dox increased pro-inflammatory cytokines (TNF-α, IL-6, IL-1β) and NO, likely contributing to an acute inflammatory response that facilitates immunogenic cell death." (PMID 41304843, 2025). "Neutrophils also contribute to cancer progression by releasing cytokines and growth factors, such as IL-6, TNF, epidermal growth factor, hepatocyte growth factor (HGF), and platelet-derived growth factor." (PMID 40027124, 2025). "Baicalin reduces anorexia by inhibiting cytokine expression (TNF-α and IL-6), prevents muscular atrophy by reducing MuRF1 and atrogin-1 expression, and inhibits NF-κB activation in a cancer cachexia model." (PMID 41011274, 2025). "Various studies consistently link NF-κB to cancer progression, notably its role in resisting TNF-α-induced apoptosis by enhancing ROS levels and antioxidant enzyme activities, thereby preventing cell death." (PMID 39860214, 2025). "Meanwhile, astrocytes engage in bidirectional communication with cancer cells and drive their aggressive growth and metastasis by secreting a variety of cytokines, such as IFNα, TNF-α, CXCL12, TGF-β2, IGFBP2 and CHI3L1." (PMID 41219968, 2025). "The top 20 pathways, such as IL‐17 signaling, TNF signaling, and the cancer pathway, were primarily identified through KEGG pathway enrichment." (PMID 40119640, 2025). "For instance, n-3 PUFAs have been shown to suppress levels of IL-6 and TNF-α in cancer patients, as well as reduce IL-17A-mediated inflammation and IL-11 expression in hepatocytes during acetaminophen-induced hepatotoxicity." (PMID 40704145, 2025). "Immunogenic DCs secrete a set of proinflammatory cytokines (TNF-α, IL-6, 8 and 12), which improve the clinical outcomes in cancer patients." (PMID 40136652, 2025). "A low concentration of TNF hinders the proliferation of some cancers, but a high concentration stimulates the production of IL-6 by stimulating monocytes, macrophages, lymphocytes, and neutrophils." (PMID 39802656, 2025). "Pro-inflammatory cytokines like IL-6 and tumor necrosis factor-alpha (TNF-α) activate survival signaling pathways in cancer cells, such as the STAT3 and NF-κB pathways." (PMID 40356750, 2025). "Carriers of the HLA-DQA105 allele exhibited increased immunogenicity when treated with TNFα antagonists, indicating the potential relevance of HLA-DQA1 to immune modulation in cancer therapy." (PMID 41009979, 2025). "The stabilisation of RIPK1’s scaffold function facilitates the assembly of complex I and activates NF-κB signalling in the TNF pathway in cancer cells." (PMID 41334873, 2025). "T-lymphocytes directly attack cancer cells while B lymphocytes act via cytokines like interferon-gamma and tumor necrosis factor-alpha." (PMID 41394347, 2025). "Interferon γ (IFN-γ) or lipopolysaccharide (LPS)-stimulated M1 macrophages elevate pro-inflammatory cytokines, such as tumor necrosis factor (TNF)-α, Interleukin (IL)-6, and IL-12 and promote anti-cancer immune responses." (PMID 40604704, 2025).
cancer (continued). "The current view is that, on the one hand, activated immune cells secrete large amounts of inflammatory and other mediators in cancer (e.g., NF-κB, TNF-α, IL-1β, IL-6, etc.), affecting the function of distant organs, such as the heart." (PMID 40182041, 2025). "As an anti-cancer agent, resveratrol also inhibits the tumor necrosis factor (TNF), a cytokine that lays a role in immune cell activation, differentiation, cell migration, and angiogenesis." (PMID 40362204, 2025). "In this analysis, the JUN gene in OC was present in the TNF signaling pathway indicating its relation with cell proliferation across various cancers." (PMID 41186627, 2025). "KEGG pathway analysis revealed that SLC25A1 knockdown significantly upregulated several inflammatory and immune pathways, including TNF, IL-17, NK cell-mediated cytotoxicity, which inhibit cancer development." (PMID 39881208, 2025). "Specifically, in colorectal cancer, TNF-α has been shown to enhance the invasive and metastatic potential of cancer cells by promoting epithelial–mesenchymal transition (EMT)." (PMID 40563999, 2025). "For example, the SASP factor TNFα can induce ROS-dependent apoptosis in human-derived cancer cell lines, while IL-6 initiates apoptosis in cultured neoplastic T lymphocytes." (PMID 40374593, 2025). "In the meantime, BCPO managed to block TNFα-NF-κB axis activation in a wide variety of cancer cell types to enhance apoptosis and suppresses invasion." (PMID 40333803, 2025). "In the realm of cancer cachexia, IL-6 and tumor necrosis factor- α (TNFα) are notable pro-inflammatory cytokines." (PMID 39311910, 2025). "The Mφ-CM contained a number of EMT inducers, including CHI3L1, IL-10, IL-6, IL-8, and TNF-α, which are known to play a role in cancer metastasis, migration, invasion, chemotaxis, and endothelial cell junction retraction." (PMID 40678259, 2025). "It assumes a pivotal role in oncogenesis and cancer immunotherapy, where the upregulation of TNFα (Tumor Necrosis Factor-alpha)-dependent pathways contributes to the advancement of BC to more advanced stages." (PMID 40575382, 2025). "Association of baseline TNF-α, GNRI and the nutrient-inflammation interaction score (NIIS) with incident cancer: Cox proportional-hazards models (hospital cohort, N = 415)." (PMID 41473193, 2025). "The abnormal expression of MARCH8 leads to the downregulation of several immunomodulatory receptors, such as MHC I, HLA 2.1, and TNF-related apoptosis, indicating its potential as a promising target in cancer immunotherapy." (PMID 39881438, 2025). "A recent study has demonstrated that GSDME is specially cleaved by activated Caspase-3 in response to TNFα plus cycloheximide (CHX) to generate GSDME-NT that is responsible for inducing pyroptosis in cancer cells." (PMID 40103680, 2025). "Tumor necrosis factor alpha (TNF-α) contributes to cancer-related inflammation and angiogenesis through nuclear factor kappa B (NF-κB) activation." (PMID 41409273, 2025). "TNF and IL6 inhibitors can increase the incidence of some malignant tumors and the risk of Mycobacterium tuberculosis reactivation." (PMID 40565149, 2025). "Regarding overall cancer risk, a French population-based study from 2023 on pediatric-onset IBD reported an HR from 6.1 to 7.4 in patients under therapy with anti-TNFα and combination therapy." (PMID 40361323, 2025). "TNF-α functions as a central inflammatory cytokine, linking chronic inflammation to cancer progression." (PMID 41259576, 2025). "CD40 is a transmembrane cell surface glycoprotein of the tumor necrosis factor (TNF) superfamily, expressed on stromal and cancer cells, APCs, and B cells." (PMID 41086813, 2025). "In vivo, luteolin decreases TNF-α and IL-6 levels, suppresses muscle protein breakdown genes (MuRF1 and atrogin-1), and prevents cancer-induced muscle wasting." (PMID 41011274, 2025).
cancer (continued). "Fig. (2B) shows the top 20 signaling pathways, including various cancer-associated signaling pathways, apoptosis signaling pathways, Epstein-Barr virus (EBV) infection, TNF signaling pathway, and IL-17 signaling pathway." (PMID 38910476, 2025). "A systematic review and meta-analysis of 63 studies indicated that circulating TNF and CRP were associated with DepS in cancer patients." (PMID 40289959, 2025). "A Phase I clinical trial combining certolizumab with chemotherapy reported a decreased metastasis and enhanced antitumor activity, emphasizing the role of TNF-α inhibition in reshaping the TME toward cancer suppression." (PMID 40430573, 2025). "Caution should be exercised when considering TNF antagonist therapy for patients with a history of malignancy or when considering continuing such treatment in patients who develop a malignancy." (PMID 40095618, 2025). "Among 520 IBD patients with a prior history of cancer, 62% were treated with thiopurines alone, 34% were treated with a combination of thiopurines and anti-TNF agents, and 4% were treated with anti-TNF agents alone." (PMID 40227584, 2025). "First, regarding cytokines in AF, the prognostic impact of inflammatory cytokines in patients with malignant tumors has been investigated in a study that reported the presence of IL-1β, IL-6, IL-8, IL-12, TNF-α, and IL-10 in AF." (PMID 39755760, 2025). "Vitamin D3 supplementation can significantly reduce TNF-α levels in the bloodstream of cancer patients." (PMID 41184249, 2025). "Simultaneously, TNF - α can induce apoptosis in cancer cells through the activation of the caspase cascade." (PMID 39980561, 2025). "The expression of TLR4 promotes the secretion of cancer‐promoting factors by macrophages, including IL‐6, IL‐23p23, and TNF‐α, enhancing inflammation and cancer growth." (PMID 40547943, 2025). "Because the rates of all-cause death (including cancer) and pulmonary embolism were higher with TOFA 10 mg twice daily than with the TNF inhibitor, the dose of this drug was reduced to 5 mg twice daily during the study." (PMID 40282506, 2025). "TNF-α functions as a proinflammatory cytokine that is involved in inflammation and cancer, including cellular differentiation, proliferation, and apoptosis." (PMID 40341222, 2025). "THGP-treated macrophages showed enhanced phagocytosis of foreign substances and cancer cells, along with increased expression of the IL-1β and TNF-α genes." (PMID 40141094, 2025). "Cancer cells can induce a persistent, low-grade systemic inflammatory state by releasing various cytokines and chemokines, such as interleukin-6 (IL-6) and tumor necrosis factor-alpha (TNF-α)." (PMID 41141695, 2025). "In those studies, no digital technologies were applied, and only isolated cytokines, such as IL-6 or TNF-α were examined in a single type of cancer." (PMID 40498221, 2025). "The dual roles of TNF-α and IL-17 in cancer emphasize the need for a nuanced approach to cancer immunotherapy." (PMID 40801630, 2025). "The TNF signaling pathway, which belongs to the exogenous death receptor signaling pathway, plays a pivotal role in cancer immunity and inflammatory reactions." (PMID 39440769, 2025). "Inflammatory mediators, including interleukins, tumor necrosis factor-alpha (TNF-α), and prostaglandins, modulate the behavior of cancer cells and surrounding stromal cells." (PMID 40256426, 2025). "In this retrospective cohort of patients with AS treated with TNF inhibitors and followed for a mean duration of seven years, the overall cancer incidence was 323 per 100,000 person-years." (PMID 41302997, 2025). "TGFβ1 controls the activities of inflammatory genes like IL-2 and TNF-α, which is a specific way that it links inflammation to cancer." (PMID 39811247, 2025). "The underlying mechanisms lie in that cancer cells can secrete cytokines, such as IL10, IL12, IL 6, and TNF, facilitating M2-like polarization, then exerting immunosuppressive effects, and finally accelerating cancer progression." (PMID 39963673, 2025).
cancer (continued). "Regular clinical monitoring and adherence to clinical guidelines for cancer screening remain paramount in managing patients receiving long-term anti-TNFα therapy." (PMID 40282506, 2025). "IFN-γ is a master regulator of MHC class I/II expression and tumor antigen presentation, while TNF-α directly induces cancer cell apoptosis through caspase activation." (PMID 40722845, 2025). "Cytokines such as IFN-γ and TNF-α were significantly elevated in the spleen and tumor microenvironment, supporting the potential of this approach for targeted cancer therapy." (PMID 41228373, 2025). "Studies have shown that antibiotic-induced dysbiosis accelerates cancer progression, such as LC, by reducing immune response, including lower TNF-α levels and impaired leukocyte trafficking, leading to fewer activated CD8+ T cells in tumors." (PMID 40563468, 2025). "Here, we describe that both human and mouse Tregs produce TNF in physiological conditions, in several mouse organs, and in mouse models of chronic inflammation and cancer." (PMID 40977146, 2025). "Sonkusre’s findings revealed that SeNPs led to an increase in TNF, ultimately resulting in the activation of cancer cell necrosis." (PMID 40388455, 2025). "NK cells kill cancer cells by releasing perforin and granzyme and triggering apoptosis through Fas/FasL and tumor necrosis factor (TNF)‐related apoptosis‐inducing ligand pathways." (PMID 40547943, 2025). "One of the main mechanisms is the excessive production and secretion of cancer-related cytokines, particularly tumor necrosis factor alpha (TNF-α), interleukin-6 (IL-6), interleukin-1 (IL-1), and C-reactive protein (CRP)." (PMID 40862802, 2025). "TNF-α secretion by myeloid cells is induced by the activation of TLR2:TLR6 complexes by cancer-secreted vesicles, thereby promoting the growth of metastatic tumors." (PMID 40443670, 2025). "Data revealed that the mean numbers of IFN-γ/TNFα-specific ELISPOTs were significantly greater (in most cases) in HuTCR-T1 γδ T cells compared to WT γδ T cells across all tested cancer cell lines and most tissues." (PMID 40801630, 2025). "Consistent with this phenotype, PT-associated macrophages expressed inflammatory cytokines (TNF, IL6) and pro-tumorigenic factors (CCL2, CCL3, CCL4, CXCL16) linked to cancer progression and invasiveness." (PMID 41346635, 2025). "While specific evidence supporting these interventions in HL survivors is lacking, cognitive behavioral therapy improves sleep hygiene, reduces proinflammatory cytokines (i.e., IL-6, TNF-α) and improves immune function in other cancer survivor populations." (PMID 41300993, 2025). "Chronic inflammation, a key cancer risk factor, promotes aberrant AID expression via TNFα-NF-κB signaling in inflammation-driven cancers like H. pylori-associated gastric cancer and colitis-related colon cancer." (PMID 40270606, 2025). "The adjusted cancer incidence rates per 1000 person-years were 41.4 (95% CI: 30.9–57.6) in the anti-TNF group and 33.6 (95% CI: 24.5–48.8) in the vedolizumab group." (PMID 40227584, 2025). "Chronic inflammation, characterized by the activation of tumor necrosis factor‐alpha (TNF‐α) and NF‐κB, contributes to the development of various cancers." (PMID 40236776, 2025). "Mouse (MC38) and human carcinoma (Caco2) cell lines were more resistant to cell death when exposed to the same doses of TNF-α, cytotoxic drugs, and X-ray irradiation compared to mouse-derived organoids." (PMID 40170863, 2025). "In this study, SFN-NLPs administration significantly suppressed the expression of NF- κB, COX-2, and TNF-α in carcinoma cells." (PMID 41291551, 2025). "The enrichment analysis showed cross genes were closely related and enriched in the cancer regulation and the TNF signal pathway." (PMID 37246319, 2024). "Atezolizumab, a monoclonal antibody intended the PD-L1, activates the immune system to combat cancer cells, leading to the release of pro-inflammatory cytokines like IL-6 and TNF-α." (PMID 38367261, 2024).